AFP (alpha fetoprotein)
Diseases named in the same sentence as AFP in open-access papers (continued):
Sharing a sentence is not in itself a finding about the gene and the disease.
liver cirrhosis (continued). "However, many patients with non-malignant chronic liver diseases, such as 15–58% of those with chronic hepatitis and 11–47% of those with liver cirrhosis, have elevated AFP concentrations." (PMID 27070780, 2016). "Besides CTSB expression level, tumor size, serum AFP, liver cirrhosis, stage, tumor recurrence, and tumor differentiation were also significantly correlated with overall survival in univariate analysis." (PMID 26896959, 2016). "A variant FGFR4 allele may be an indicator for HCC in liver cirrhosis, the AST/ALT ratio, and the AFP level." (PMID 25860955, 2015). "Most of the HCC patients in the four cohorts were men (85.5%), were carriers of hepatitis B virus (HBV) (82.6%), had liver cirrhosis (72.8%), had an elevated serum alpha-fetoprotein (AFP) level (61.7%), and had a single tumor nodule at the time of resection (83.7%)." (PMID 25576919, 2015). "Moreover, this is the first study that correlated liver cirrhosis, the AST/ALT ratio, and the AFP level caused by FGFR4 polymorphic variants and their association with HCC." (PMID 25860955, 2015). "Moreover, low expression of AZGP1 was notably more prevalent in patients with poor tumor differentiation, serious liver cirrhosis, high serum AFP level and short survival time." (PMID 22625427, 2012). "In addition, the AFP test has a high false-positive rate of ∼20% among patients with chronic hepatitis and 20–50% among those with liver cirrhosis." (PMID 22808038, 2012). "Furthermore, AZGP1 expression in HCC significantly associated with several clinicopathological parameters, including serum AFP level (P = 0.013), liver cirrhosis (P = 0.002) and tumor differentiation (P = 0.025)." (PMID 22625427, 2012). "However, other clinical characteristics, including age, sex, preoperative serum α-fetoprotein (AFP), liver cirrhosis, Child–Pugh score, preoperative treatment, tumor number and differentiation were not significantly related to the expression of LRP1." (PMID 22427881, 2012). "However, the diagnostic significance of circulating hsa-miR-21-5p in liver cirrhosis or AFP-negative HCC cases has not yet been studied." (PMID 36834570, 2023). "Additionally, Korea has a separate health check-up program that provides free-of-charge abdominal sonography and AFP test twice a year for patients with chronic hepatitis (viral hepatitis B, viral hepatitis C, and liver cirrhosis) as surveillance tests for HCC." (PMID 35329799, 2022). "In contrast to AFP, CA19-9 levels ≤ 37 U/mL were significantly associated with higher values of alanine aminotransferase (ALT), AST, serum albumin, Child–Pugh score, and total bilirubin (TBil), as well as with positive hepatitis B surface antigen (HBsAg) and liver cirrhosis." (PMID 36258212, 2022). "Compared with AFP and CA125, miR-212 has a more significant correlation with Child-Pugh Classification, MELD score and MELD score, as well as associated with the progression of hepatitis B-related liver cancer, esophageal varices, ascites, and liver cirrhosis progress associated with HBV infection." (PMID 33869059, 2021). "Together with AFP, the three miRNAs (miR-21, miR-122, miR-192) may serve as effective biomarkers to improve diagnostic therapy for HCC in HBV-positive patients, in particular, HBV-related liver cirrhosis with normal AFP levels or HCC with small tumor sizes." (PMID 34771525, 2021). "However, other features including age, gender, ALT, liver cirrhosis, tumor encapsulation, and serum AFP level showed no significant prognostic associations with OS or RFS." (PMID 32756012, 2020). "Likewise, the aetiology of liver cirrhosis and the trend for the application of lower AFP thresholds (<20 ng/mL) to monitor HCC recurrence may affect the robustness of the conclusion." (PMID 31600291, 2019). "Besides, patients with chronic hepatitis or liver cirrhosis also have higher level of AFP." (PMID 29717027, 2018).
liver cirrhosis (continued). "Furthermore, tumor markers, such as AFP, are highly variable among individuals and might be influenced by the presence of chronic hepatitis C or liver cirrhosis." (PMID 29771954, 2018). "However, the expression failed to be associated with other clinical pathological factors such as gender, age, hepatitis B surface antigen, hepatitis C virus (HCV), preoperative AFP, liver cirrhosis, BCLC stage, tumor size, tumor number, vascular invasion, and tumor differentiation." (PMID 27689999, 2016). "In conclusion, our data suggest that HBeAg seroconversion and liver cirrhosis are associated with the occurrence of HCC and that a surveillance system with regular measurement of AFP to watch for the occurrence of HCC may be mandatory for children and young patients with chronic HBV infection." (PMID 27748053, 2016). "In addition, serum MDK was not significantly higher in the liver cirrhosis group than that in healthy group (0.15 versus 0.125 ng/mL; P = 1.559), in contrast to serum AFP which was significantly elevated in the liver cirrhosis group when compared to healthy group (17.5 versus 1 ng/mL; P = 0.0001)." (PMID 25737783, 2015). "However, no statistical difference was identified in the expression of pluripotent genes when compared with other clinicopathological factors, including age, gender, hepatitis B surface antigen (HBsAg), AFP, liver cirrhosis, tumor number, tumor encapsulation and TNM stage." (PMID 23599755, 2013). "However, other clinical characteristics, including age, sex, hepatitis B surface antigen positivity, liver cirrhosis, preoperative serum alpha-fetoprotein, preoperative serum carbohydrate antigen 19-9 (CA19-9), Child-Pugh score and tumor size, were not significantly related to Capn4 expression." (PMID 23349941, 2013). "These included significant elevation activity of ALT, decompensation of liver cirrhosis, HCC dissemination, and increased alpha-fetoprotein concentration." (PMID 41517592, 2026). "Multivariate Cox regression analysis was conducted, including gender, age, family medical history, viral infection, liver cirrhosis, Child Pugh score, BCLC stage, alpha fetoprotein (AFP), tumor number, and maximum tumor diameter." (PMID 41049859, 2025). "Multivariate Cox regression analysis further confirmed that age, AFP, TNM stage, liver cirrhosis, tumor capsule, and the expression levels of CK19, Ki67, and β-catenin were independent prognostic factors." (PMID 41388520, 2025). "Both AFP and miR-485-5p were able to discriminate HCC patients from those with liver cirrhosis (p < 0.001)." (PMID 40208438, 2025). "To further study the role of TBS score in predicting HCC prognostic outcome, we performed a subgroup analysis of age, sex, AFP level, MVI, HBV-DNA, liver cirrhosis, and BCLC staging, Liver capsule involvement, and depicted a forest plot." (PMID 39555448, 2024). "Compared to chronic HBV and liver cirrhosis, circ_0028861 exhibited downregulation in HCC patients and showed greater significance than AFP in diagnosing small, early-stage, and AFP-negative HCC." (PMID 38476233, 2024). "Specifically, more patients in our study had liver cirrhosis, CTP class B, alcoholic liver disease, BCLC stage C, ascites, larger maximum tumor diameter, and higher AFP levels." (PMID 38429725, 2024). "The data demonstrate clear clinicopathological associations between C. sinensis infection and factors, such as gender, BCLC stage, liver cirrhosis, MVI, AFP, CA19-9, circulating eosinophils and complements." (PMID 38285640, 2024). "The subgroup analysis included age, sex, AFP level, MVI, mode of operation, HBV-DNA, liver cirrhosis, hepatic capsule involvement, and BCLC staging." (PMID 39555448, 2024). "The serum levels of AFP-L3 (i.e., Lens culinaris agglutinin-reactive AFP, a fucosylated glycoform of AFP) and Des-gamma carboxyprothrombin (DCP) can serve as biomarkers for the early detection of HCC in patients with hepatitis or liver cirrhosis." (PMID 38668286, 2024).
liver cirrhosis (continued). "The combined use of EV miR-122, miR-148a, and AFP improved the AUROC to 0.931 (95% CI: 0.857–0.973), making it effective for distinguishing early HCC from liver cirrhosis." (PMID 39451600, 2024). "Statistical analysis revealed significant differences in gender, age, BCLC stage, liver cirrhosis, MVI, AFP, and HBsAg between the HCC_Cs group and C. sinensis negative HCC group (P < 0.05)." (PMID 39840062, 2024). "Our study demonstrates clear clinicopathological associations between C. sinensis and HCC, such as gender, BCLC stage, liver cirrhosis, MVI, AFP, CA19-9, circulating eosinophils and complements." (PMID 38285640, 2024). "The results of the univariate regression analysis indicate that night variables, including age, gender, AFP, PIVKA-II, AST, ALT, ALB, PT, and TP, were significant predictors of HCC when compared with HBV infection or liver cirrhosis." (PMID 37189543, 2023). "The univariate and multivariate analyses indicated the diagnostic value of various clinical factors (including lnc-MyD88 and AFP) in HBV-related HCC group, and the HBV-related liver cirrhosis group is the control." (PMID 36793272, 2023). "The results of the adjustment for conventional clinical patterns, including gender, diagnostic age, pathologic stage, vascular invasion, and serum AFP level, HBV infection, Child–Pugh score, tumor number, and liver cirrhosis status." (PMID 36975415, 2023). "Considering that multiple factors affect survival (such as TNM stage, tumor grade, tumor size, AFP level, BCLC stage, and liver cirrhosis), the multivariate Cox regression analysis was performed." (PMID 37551111, 2023). "All of the studies included were random controlled trials, with matched number of patients, sex distribution, tumor size, liver cirrhosis status, Child-pugh score, ECOG, pre-operative alpha-fetoprotein(AFP) in each trial." (PMID 37730533, 2023). "For univariate analysis, age, sex, diabetes status, γGTP, and AFP were entered, and FIB-4 index, new formula score, and liver cirrhosis were added to each of the three models." (PMID 37733802, 2023). "A combination of AFP and circ_0070396 performs better than a single marker in the differentiation of HCC from healthy donors, chronic HBV, and liver cirrhosis patients, with AUC values of 0.94, 0.85, and 0.75, respectively." (PMID 37765333, 2023). "Sex, increasing age, liver cirrhosis, an episode of ACLF, alcohol consumption, family history of HCC, TBil, albumin, AFP, platelet count, HBV DNA, ALT, and AST were introduced into the univariate Cox model." (PMID 36339647, 2022). "A statistical analysis of sex, age, alanine aminotransferase (ALT), aspartate aminotransferase (AST), total bilirubin (TBIL), alpha-fetoprotein (AFP), hepatitis B surface antigen, and liver cirrhosis between the two groups was performed." (PMID 36276135, 2022). "In our subgroup analysis based on various clinical characteristics, the RFS was significantly higher in the subgroups of patients with AFP > 15 (p = 0.024), ALBI stage II/III (p = 0.01), liver cirrhosis (p = 0.007) and microvascular invasion (p = 0.001)." (PMID 35208582, 2022). "On univariate analyses, several factors including sudden onset, hypertension, liver cirrhosis, Child-Pugh grade, hemoglobin (Hb), TB, serum albumin (ALB), AFP, hepatitis B virus surface antigen (HBsAg), and tumor size were potential predictors of STRHCC." (PMID 35155255, 2022). "The MKN1-AS levels are not significantly correlated with gender, age, tumor size, differentiation, satellite foci, AFP level, quantification of hepatitis B virus (HBV) DNA, or liver cirrhosis (p > 0.05)." (PMID 35579449, 2022). "We measured total AFP and %L3 in the serial serum specimens collected over time, in patients with ALT flare, liver cirrhosis, HCC, and recurrent HCC and along with radiological examination." (PMID 35458505, 2022).
liver cirrhosis (continued). "This is because AFP can be elevated not only in the setting of HCC, but also in chronic hepatitis, liver cirrhosis, or ALT flare in CHB, which limits the specificity of AFP." (PMID 35458505, 2022). "In the first study, glypican-3 performed similar to AFP (AUROCs of 0.78 and 0.79, respectively), while their combination had good accuracy (AUROC = 0.94) in discriminating HCC from liver cirrhosis." (PMID 33918270, 2021). "The presence of liver cirrhosis, serum CA19-9, and AFP levels are also supportive of the differential diagnosis." (PMID 34804918, 2021). "Patients with IMCC had lower a-fetoprotein (AFP) levels than those with HCC(P < 0.001), and the IMCC group had fewer cases of liver cirrhosis than the HCC group (P < 0.001)." (PMID 34848818, 2021). "We further assessed the discriminative performance of GINS4 between low AFP-expressing HCC individuals and liver cirrhosis patients from the GSE25097 and GSE63898 datasets." (PMID 33842367, 2021). "Formerly, various factors were established to be prognostic indicators for HCC, such as advanced age, male gender, tumor size, high alpha-fetoprotein (AFP) level, and the presence of liver cirrhosis." (PMID 34837928, 2021). "ROC analysis showed that IGF2 had the highest area under the curve (AUC) for discriminating HCC from liver cirrhosis (0.86), followed by IL6 (0.82), AFP (0.72), and platelet count (0.6)." (PMID 34714420, 2021). "When the training dataset and the validation dataset were combined and 127 liver cirrhosis cases were included as precancerous HCC lesions, the trends of AFP and the PP value as biomarkers in the progression of HCC were analyzed." (PMID 32443439, 2020). "AFP, the traditional biomarker for HCC, has been proved with low specificity in predicted HCC patients from CH or patient with liver cirrhosis, and it has also been validated in this study." (PMID 32692470, 2020). "The two groups were similar in their distributions of age, sex, HBV infection, AFP and CEA levels, Edmondson-Steiner grade, fibrosis stage, the presence of liver cirrhosis, and fatty liver (P > 0.05)." (PMID 32576283, 2020). "Multiple reaction monitoring (MRM) analysis of 41 proteins revealed 10 proteins were differentially expressed in patients with liver cirrhosis and HCC patients with normal AFP." (PMID 31979338, 2020). "Regarding the cost of care, only one third of patients with liver cirrhosis and less than half of HCC patients were able to afford testing for AFP." (PMID 33357229, 2020). "The Serum alpha-fetoprotein was increased 99, 79, 90 and 39 folds in HCC patients as compared to healthy subjects, and patients with HCV, NASH and liver cirrhosis." (PMID 33369452, 2020). "The mean serum AFP, CA19-9 and CEA levels were clearly higher in the PHC group than in the other liver cirrhosis and control groups." (PMID 31205886, 2019). "In this study, we found that HBV infection was associated with 10-year earlier onset and higher proportions of positive AFP, positive CA19-9, the presence of liver cirrhosis, high direct bilirubin, advanced BCLC stage, and the presence of MVI in HCC." (PMID 31179237, 2019). "Serum AFP, CEA, and CA19-9 levels in the PHC group were significantly higher compared to those with liver cirrhosis and healthy control groups (P < 0.03)." (PMID 31205886, 2019). "Univariate survival analysis revealed that CBX3/HP1γ expression, AFP, GGT, liver cirrhosis, tumor size, tumor number, vascular invasion, and tumor capsule were significantly associated with OS." (PMID 31375643, 2019). "Serum alpha-fetoprotein (AFP), cancer antigens (CA19-9), and carcinoembryonic antigen (CEA) levels were in patients with primary hepatic cancer (PHC), Liver cirrhosis, and the healthy population can be used as a screening and prognostic tool." (PMID 31205886, 2019).
liver cirrhosis (continued). "Subgroup analysis was done based on various factors correlated with the prognosis (TTR and OS) of HCC patients with PVTT after resection, including age, degree of PVTT, Edmondson's grade, tumor number, AFP level, HBV DNA status, and liver cirrhosis." (PMID 31566899, 2019). "Kaplan-Meier analysis showed that the patients with high expression of HOXC6, high AFP level, high gamma-glutamyltransferase (GGT) level, liver cirrhosis, larger tumor or vascular invasion had poorer OS time (all P < 0.05)." (PMID 29348394, 2018). "Kaplan-Meier analysis revealed that the patients with low CLCA4 expression (P < 0.001), high AFP level (P < 0.001), high GGT level (P = 0.017), liver cirrhosis (P = 0.007), larger tumor (P < 0.001) and vascular invasion (P < 0.001) had shorter OS time." (PMID 30312171, 2018). "The present study confirms that increased liver stiffness, serum alpha fetoprotein level, hepatitis C virus etiology and portal hypertension clinically-based (PH-CB) are predictors of the presence of HCC in liver cirrhosis patients." (PMID 29947694, 2018). "Older age; male sex; liver cirrhosis and elevated serum levels of ALT, AST, AFP and HCV RNA were predictors of HCV-related HCC." (PMID 30237482, 2018). "In addition, a large-scale multicenter study was performed with patients affected by liver diseases including HCC, chronic hepatitis B virus (HBV) or liver cirrhosis to assess whether DKK1 could serve as an alternative biomarker to alpha-fetoprotein (AFP) for HCC diagnosis." (PMID 27367730, 2016). "There was no statistical difference between the two groups in terms of the patients' age, sex, percentages of liver cirrhosis, Child-Pugh score, platelet count, ALT level, and tumor markers AFP and DCP." (PMID 26494948, 2015). "A multivariate Cox model adjusted for AFP, GGT, liver cirrhosis, tumor size, satellite nodule, vascular invasion and Cripto-1 expression was performed." (PMID 26375669, 2015). "A multivariate Cox model adjusted for AFP, GGT, liver cirrhosis, tumor size, tumor number, satellite nodule, vascular invasion and Cezanne expression was performed." (PMID 25638165, 2015). "The median serum AFP level in HCC was 270.00 ng/ml, which was higher compared with the liver cirrhosis (7.26 ng/ml), chronic hepatitis (13.80 ng/ml) and healthy control (2.33 ng/ml) samples." (PMID 24137480, 2013). "In summary, primary hepatic EST is an extremely rare condition but should be considered as a differential diagnosis to HCC, particularly in young female patients without hepatitis infection or signs of liver cirrhosis and with elevated AFP levels." (PMID 41523302, 2026). "While the lower expression of MT2P1-RNA is positively related to a higher quantity of serum Alpha-fetoprotein (AFP) (p < .05), more advanced TNM stages (p < .05), more tumor microsatellite formation (p < .05), detectable invasion of venous (p < .05), and later liver cirrhosis stages (p < .05)." (PMID 40407049, 2025). "However, it is worth noting that MDK showed greater sensitivity compared with AFP in HCC diagnosis, especially in the early stages, highlighting its potential as a novel marker, especially in differentiating HCC from liver cirrhosis." (PMID 38247828, 2024). "The results showed that TBS > 10.77 was the risk factor related to OS and RFS for all age groups, sex, BCLC stage, preoperative AFP level, no liver cirrhosis, HBV-DNA, mode of operation, MVI, and hepatic capsule involvement." (PMID 39555448, 2024). "Non‐cirrhotic control groups may overestimate the diagnostic accuracy of each individual biomarker as well as the combination of them in the detection of HCC, as it has been observed that liver cirrhosis significantly impacts serum PIVKA‐II and AFP levels." (PMID 38361401, 2024). "A seven-year-older mean age, approximately 20% higher prevalence of DM, 50,000/μL lower platelet count, and 26 ng/mL higher alpha-fetoprotein were observed in patients with liver cirrhosis than in non-cirrhotic patients." (PMID 38473248, 2024).